SP1 (Sp1 transcription factor)
Diseases named in the same sentence as SP1 in open-access papers (continued):
Sharing a sentence is not in itself a finding about the gene and the disease.
cancer (continued). "We find six pan-cancer subnetwork signatures which relate to cell cycle, immune response, Sp1 regulation, collagen, muscle system and angiogenesis." (PMID 27633916, 2016). "For stance, it had been reported that elevated Sp1 contributes to overexpression of multiple oncogenic genes in human cancers, including PDAC." (PMID 27713167, 2016). "Two functional SNPs (SNP285G > C; rs117039649 and SNP309T > G; rs2279744) have previously been reported to modulate Sp1 transcription factor binding to the promoter of the proto-oncogene MDM2, and to influence cancer risk." (PMID 27624283, 2016). "As to cancer, Sp1 was found to be elevated in most tumors responsible for unfavorable phenotypes via transcription activation." (PMID 27713167, 2016). "The functional and genomic effects of Sp1, Sp3 and Sp4 were investigated by RNAi in several different cancer cell lines." (PMID 26967243, 2016). "Median follow-up duration was 139.8 months and 29 patients (14.4%) had distant recurrence of cancer; 20 patients (19.8%) with high SP1 expression had tumor recurrence in contrast to only nine patients (8.9%) with low SP1 expression." (PMID 27545642, 2016). "Subsequently, we knockout Sp1 expression of the cancer cells and found that PLD1 decreased concomitantly." (PMID 27713167, 2016). "Most studies in cancer cells have focused on Sp1 and there is evidence showing that knockdown of Sp1 by RNA interference (RNAi) in cancer cell lines inhibits cell growth, survival and migration/invasion." (PMID 26967243, 2016). "Evidences exist that both Sp1 expression and transcriptional activity are excessively increased in various types of cancers, and high expression of Sp1 is generally considered as a negative prognostic factor." (PMID 27806345, 2016). "In this review, we will discuss the diverse mechanisms of transcriptional regulation by Sp1 and their potential involvement in the adaptive response of cancer cells to hypoxic tumor microenvironments." (PMID 26703734, 2015). "On the other hand, the Sp1-HIF-1α interaction similarly suppresses the expression of cell cycle-related genes via inhibition of c-Myc binding to these genes in cancer cells." (PMID 26703734, 2015). "Recent studies have shown that gene regulation induced by metformin involves the transcription factor SP1 in cancers." (PMID 26083494, 2015). "The human endosialin (CD248) gene can be activated in some normal and cancer cells via binding of Sp1 to the promoter region under high cell density culture conditions." (PMID 26703734, 2015). "Results of this study demonstrate the importance of HULC and Sp transcription factors in HCC, suggesting that both HULC and Sp1 can be targeted by anticancer agents that are known to downregulate Sp transcription factors in other cancer cell lines and tumors." (PMID 26317792, 2015). "Sp transcription factors play a role in the proliferation, survival, migration/invasion of several cancer cell lines and we used RNAi to investigate the differential effects of Sp1, Sp3, Sp4 and HULC knockdown on HCC cell proliferation and survival." (PMID 26317792, 2015). "Sp1 is a sequence-specific DNA binding protein involved in the transcription of many important regulatory genes correlated to cancer development." (PMID 26041879, 2015). "Egr-1 is known to be upregulated in response to hypoxia in cancer cells and competes with Sp1 for binding to the GC-box." (PMID 26703734, 2015). "Treatment of cancer cells with this antibiotic augments Sp1 activity under normoxia, resulting in elevation of HIF1A transcript levels, potentially by increasing binding activity rather than by increasing the protein level." (PMID 26703734, 2015).
cancer (continued). "One plausible possibility is that Sp1 contributes to fine-tuning HRE activity for the appropriate adaptation of cancer cells to dynamically changing hypoxic conditions." (PMID 26703734, 2015). "All of the recent studies revealed that ETS1 and SP1 are responsible for cancer cell invasion via modulation of MMPs." (PMID 26177288, 2015). "Sp1 expression and activity are up-regulated in many cancers, correlating with advanced stage and poor prognosis." (PMID 26536461, 2015). "Clinical studies also indicated that Sp1 expression was aberrantly elevated in various types of cancer, and closely correlated to TNM classification, tumor invasion and lymph node metastasis." (PMID 25918249, 2015). "Sp1 is known to be overexpressed or overactivated in many types of cancers and plays a role in carcinogenesis." (PMID 25923237, 2015). "Deregulated expression of oncogenes or transcription factors such as specificity protein 1 (Sp1) is observed in many human cancers and plays a role in tumor maintenance." (PMID 25738304, 2015). "It has been reported that Mithramycin is a gene-selective Sp1 inhibitor that confers a biological intersection between cancer and neurodegeneration." (PMID 26484141, 2015). "HRE and Sp1 sites were found to collaborate to enhance the promoter activity of these genes in a HIF-1α-dependent manner in several types of cancer cell exposed to hypoxia or hypoxia mimetic stimuli." (PMID 26703734, 2015). "Overall, the interaction between Sp1 and HIFs on the gene-regulatory regions in cancer cells seems to be regulated via differential control of PAS domain phosphorylation." (PMID 26703734, 2015). "Sp1 is known to be displaced from the chromatin and remains stable in mitotic cancer cells, and to be reserved for daughter cells, thus apparently facilitating a quick start to the execution of cell growth." (PMID 25398907, 2014). "Sp1 is a ubiquitously expressed transcription factor that is involved in modulating normal and tumorigenic gene expression in multiple cancers." (PMID 24626475, 2014). "Previous studies suggested that mithramycin A (Mith) inhibits the growth of various cancers by decreasing Sp1 protein." (PMID 25418289, 2014). "Although Sp1 deregulation is beneficial for treating tumor cells, it is reported that overexpression of Sp1 induces apoptosis of untransformed cells or cancer cells." (PMID 24423061, 2014). "Few studies have investigated the regulation of Sp1 protein by proteasome-dependent degradation as a possible control mechanism for the regulation of Sp1 in cancer cells." (PMID 25418289, 2014). "Taken together, these results suggest a fundamental role of Sp1 in the phenotypic regulation of cancer cells, and implicate the potential application of Sp1 in cancer therapy." (PMID 25099028, 2014). "Regarding its cancer-related functions, Sp1 has been suggested to be a novel target for cancer therapy." (PMID 24423061, 2014). "Sp1 can be used as an effective therapeutic target in cancer research, and HPB242 are potential cancer drugs or adjuvants as chemotherapeutic agents for OSCC." (PMID 24423061, 2014). "Reduction of body weight was minimal, indicating that Mith was a good therapeutic candidate for treatment of cancers in which Sp1 is involved in promoting and developing disease." (PMID 25418289, 2014). "These previous findings show that the significance of SP1 involvement in cancer progression have been controversial." (PMID 25060396, 2014). "For example, Sp1 accumulates in most of cancers; knockdown of Sp1 expression decreases cell proliferation, but Sp1 overexpression also attenuates cancer cell growth." (PMID 24519909, 2014). "Other inhibitory compounds for SP1 will be clinically applied for various diseases, in addition to cancer 41,42." (PMID 25060396, 2014). "Our previous studies also showed that regulation of Sp1 protein stability by phosphorylation and sumoylation contributed to its expression in the early and late stages of cancer, respectively." (PMID 24519909, 2014).
cancer (continued). "Here, we have shown that Sp1 is involved in the regulation of gene expression in A2780 human carcinoma cells treated with DIG-MSK." (PMID 25110883, 2014). "Previous studies have revealed the critical role of transcription factor Sp1 in the regulation of MMP-14 expression in cancer cells." (PMID 23394613, 2013). "ChIP assay further revealed the decreased binding of Sp1 on MMP-14 promoter in cancer cells treated with sub-cytotoxic MJ." (PMID 23394613, 2013). "For instance, EPS8 has also been shown to upregulate FOXM1, an important factor in the development and progression of certain cancers which is known to directly bind with Sp1." (PMID 24367505, 2013). "Transcription factor Sp1 plays an important role in physiological process and also in human cancer progression by regulating transcription of diverse downstream genes." (PMID 24010737, 2013). "Specificity protein 1 (SP1) is an essential transcription factor that regulates multiple cancer-related genes." (PMID 23437057, 2013). "In particular Sp1 interacts with specific regulatory elements and plays a key role in cell cycle arrest and apoptosis in carcinoma cells." (PMID 24244623, 2013). "Sp1, a cell growth and survival transcription factor, has been shown to associate with SUV39H1 upon hydrogen peroxide treatment in an epithelial carcinoma cell line, leading to growth arrest through the silencing of Sp1 target genes, including cyclin B1." (PMID 23705022, 2013). "Deregulated activity of transcription factors (TFs) of the Sp/KLF family, like Sp1, Sp3 and Sp4, and consequent over-expression of Sp-regulated genes occur frequently in human cancers." (PMID 22545098, 2012). "Although Sp1 deregulation is advantageous for treating tumor cells, it is reported that overexpression of Sp1 induces apoptosis of untransformed cells or cancer cells." (PMID 22734486, 2012). "Regarding to its cancer-related functions, Sp1 has been suggested as a novel target for cancer therapy." (PMID 22734486, 2012). "Sp1, Sp3 and Sp4 are overexpressed in multiple cancer cell lines and tumor types and Sp-regulated genes and oncogenes play an important role in cancer cell proliferation, survival, angiogenesis and inflammation." (PMID 23194063, 2012). "Previous studies by RNA interference (RNAi) show that both survivin and bcl-2 are regulated by Sp1, Sp3 and Sp4 in cancer cells." (PMID 23110215, 2012). "SP1 is a transcriptional factor that is over expressed in a variety of cancers and regulates gene expression by interacting with GC rich SP1 binding sites." (PMID 22870216, 2012). "Sp1 can be used as an effective therapeutic target in cancer research, and cafestol and kahweol are potential cancer drugs or adjuvants as chemotherapeutic agents for MPM." (PMID 22734486, 2012). "Several pathways have been described for enhanced Sp degradation in cancer cell lines and these include activation of proteasomes, caspases and ROS and also a pathway which involves nuclear export of Sp1 followed by proteolytic degradation in the cytosol." (PMID 23110215, 2012). "Sp1 has been reported to affect the tumorigenesis of many cancer types by modulating the expression of its target genes, which include oncogenes and tumor suppressor genes." (PMID 23148884, 2012). "Both Sp1 and NF-κB have been shown to be misregulated in the disease state, including various types of human cancer." (PMID 21731707, 2011). "Altogether, these findings show that Sp1 is overexpressed or overactivated in a number of cancers and that its activity plays a role in late stage of carcinogenesis." (PMID 19753117, 2009). "Microarray analysis shows that among the genes found to be differentially expressed following Sp1 overexpression there is an enrichment in genes involved in cancer, cell cycle and cell death." (PMID 19753117, 2009). "Genome-wide expression profiling identified genes involved in cancer, cell death and cell cycle as being enriched among differentially expressed genes following Sp1 overexpression." (PMID 19753117, 2009).
cancer (continued). "Analysis of the categories of genes enriched following Sp1 deregulation revealed that the highest enrichment was observed for genes belonging to the Cancer category." (PMID 19753117, 2009). "This naturally occurring insertion results in a significant 1.8-fold lower methylation of the gene in normal samples, and a 2.1-fold to 3.1-fold lower methylation in cancer that we have traced to the creation of a new Sp1/Sp3 binding site." (PMID 18725933, 2008). "Both Sp1 and Sp3 show increased expression in a number of cancers suggesting that these transcription factors are switched back on during cancer cell differentiation." (PMID 19471608, 2008). "Sp1 enhances metastatic fitness by increasing the levels of survival factors such as Bcl-2 and survivin, making cells more resistant to treatments that kill cancer cells." (PMID 41596524, 2026). "Moreover, since Sp1, Sp3 and Sp4 regulate multiple genes required for cancer cell proliferation, survival and invasion, it has been suggested the Sp TFs are non-oncogene addiction genes." (PMID 39858066, 2025). "Other group III receptor interactions with Sp1: The glucocorticoid receptor interacts with Sp1 in the regulation of monoamine oxidase A and B in neuronal-derived cancer cells, and estrogen receptor-related receptor (ERR) interacts with Sp1 to activate p21 in Hela cells." (PMID 39858066, 2025). "SP1 is a ubiquitous transcription factor crucial in cancer development." (PMID 39800760, 2025). "In summary, Sp1 is a central transcriptional regulator linking many genes and proteins critical to health and disease and affecting metabolism, glycosylation, angiogenesis, immune evasion, and cancer stemness." (PMID 40869407, 2025). "Additionally, natural compounds such as tolfenamic acid and curcumin have been reported to reduce Sp1 levels in in vitro and in vivo cancer models." (PMID 39912718, 2025). "Furthermore, reported in various cancers except for EAC as relevant to activating PI3K-Akt signaling pathway or promoting tumor through SENP3/SP1/SQLE axis, SERPINH1 was also identified as a key gene in EAC in the current study." (PMID 40872572, 2025). "Collectively, these findings suggest that SP1 inhibitors could potentially prevent or reverse metastatic progression across multiple cancer types." (PMID 39748426, 2025). "Thus, PR interaction with Sp1 modulates only a limited number of genes compared to ERα-Sp interactions in cancer cells." (PMID 39858066, 2025). "Thus, it targets TFs like E1AF (a transcription factor important for cancer metastasis) and Sp1 for their ability to metastasize cells." (PMID 40869407, 2025). "Sp1 is now recognized as a master regulator of cancer-related transcriptional programs." (PMID 40869407, 2025). "Therefore, targeting SP1 offers a compelling therapeutic avenue with the potential to modulate oncogenic transcriptional networks across multiple cancer contexts." (PMID 40884402, 2025). "Notably, applying these drugs to naturally metastatic cancer cells or cancer cells forced to migrate with SP1 overexpression markedly reduced their migratory abilities." (PMID 39748426, 2025). "Estrogen receptor: The hormonal regulation of ER-responsive genes has been investigated in breast and other cancer cell lines, and induction or repression of many of these genes by ER ligands primarily involve ER interactions with DNA-bound Sp1 and, in a few cases, Sp3 or Sp4." (PMID 39858066, 2025). "CENP-H can promote cancer growth and metastasis through PI3K/AKT, survivin, and mitochondrial apoptosis signaling mechanisms, and it can be regulated by long non-coding ribonucleic acid (lncRNA) plasmacytoma variant translocation 1 (PVT1)/miR-612, Sp1, or Sp3." (PMID 40071086, 2025). "SP1 has also been found to be related to the characteristics of cancer stem cells." (PMID 40666524, 2025). "Thus, cancer cell proliferation is modulated by SP1 translocation during the cell cycle progression, orchestrated by CDK1 and PP2A." (PMID 39860065, 2025).
cancer (continued). "PKCζ-dependent SP1 phosphorylation is involved in VEGF expression in RCC cancer cells." (PMID 39875519, 2025). "Sp1 plays a key role in regulating the cell cycle and cancer stem cells (CSCs)." (PMID 40869407, 2025). "Sp1 was the first TF identified, and the Sp1–4 subfamily is particularly important in cancer." (PMID 39858066, 2025). "The importance of PTM of Sp1 in cancer has been extensively reviewed elsewhere." (PMID 40143226, 2025). "Moreover, Sp1 overexpression in cancers is suggested to support HERV-K promoter demethylation, leading to the production of viral proteins that further contribute to pathogenicity." (PMID 40143226, 2025). "Sp1 has been shown to be indispensable during embryonic development and has been widely studied for its role in cancer biology because of its ability to transactivate genes involved in cell cycle regulation and immune system evasion, extensively reviewed elsewhere." (PMID 40143226, 2025). "Finally, with these insights in mind, we comment on the potential for Sp1-targeting therapies, such as repurposing drugs currently in use in the anti-cancer realm, and what limitations such agents would have as antivirals." (PMID 40143226, 2025). "In conclusion, JUN, NFKB1 and SP1 may jointly maintain the characteristics of cancer stem cells by regulating the stemness maintenance and telomerase activity of cancer stem cells, thus influencing the progression, treatment resistance and recurrence of BC." (PMID 40666524, 2025). "Pan‐cancer analysis demonstrated that SP1 expression is elevated in various cancer types." (PMID 41017455, 2025). "As an alternative strategy, directly targeting SP1 may offer a more precise and effective approach in cancer therapy." (PMID 40884402, 2025). "Notably, SP-1-303 demonstrates significantly reduced toxicity to normal breast epithelial cells (40-fold lower toxicity compared to cancer cells)." (PMID 39008483, 2024). "SP1 is regulated by multiple miRNAs in various human cancers." (PMID 39056681, 2024). "AP1G1 and SP1 expression levels were upregulated in different types of human cancer." (PMID 39056681, 2024). "Other E3 ubiquitin ligases can regulate cancer through Sp1 ubiquitination." (PMID 39228402, 2024). "Thus, these miRNAs either positively or negatively affect cancer progression by targeting both cancer cells per se and the cancer microenvironment via modulation of all three of SP1, MYC, and HIF1A." (PMID 39590335, 2024). "Sp1 transcription factors can serve as prognostic indicators in multiple cancers through interaction with miRNA and lncRNA to enhance the growth, viability, movement, and infiltration of cancer cells." (PMID 39228402, 2024). "Phosphorylated Sp1 is central to the regulation of multiple cancer-related genes." (PMID 39228402, 2024). "Further studies may elucidate additional phosphorylation targets and their role in biological processes to precisely define the role of Sp1 phosphorylation in cancer." (PMID 39228402, 2024). "Sp1 is a transcription factor that regulates a variety of biological processes such as cell growth, differentiation, survival, tumor progression, and metastasis, and is highly expressed in many cancer tissues." (PMID 39239650, 2024). "Sp1 is highly associated with the poor prognosis of various cancers; it is considered a non-oncogene addiction gene." (PMID 39228402, 2024). "Furthermore, Sp1 can escape growth inhibition by regulating cancer cell response to specific stresses." (PMID 39228402, 2024). "Further experiments are necessary to explore whether AP1G1 and SP1 play a precise role in these cancer types and to clarify the mechanism." (PMID 39056681, 2024).